IGFBP3 (insulin like growth factor binding protein 3)
Diseases named in the same sentence as IGFBP3 in open-access papers (continued):
Sharing a sentence is not in itself a finding about the gene and the disease.
prostate tumor (9 papers, 2007 to 2022). "CAFs derived from high grade prostate tumor harboring the highest IGFBP3 mRNA levels, exhibited resistance to the drug, compared to CAFs from low-grade tumors." (PMID 29108245, 2017). "This study enhances our understanding of a new dynamic in the prostate tumor stroma involving IGFBP3 as an EMT regulator, and its impact on the therapeutic response of cancer epithelial cells." (PMID 29108245, 2017). "IGFBP3 knockout male mice had a higher incidence of lung metastases and the invasiveness of primary prostatic tumor cells was increased over 3-fold when compared with that of wild ones." (PMID 24386080, 2013). "The highest IGFBP3 mRNA level was detected in prostate tumor with the highest Gleason score (4+5)." (PMID 29108245, 2017). "The effect of the new agent, DZ-50, on MET induction and TGF-β1-mediated prostate tumor cell migration by targeting IGFBP3, may facilitate a new therapeutic optimization platform for the treatment of advanced CRPC." (PMID 29108245, 2017). "Thus one can speculate on a potential engagement of IGFBP3 by the TGF-β1-CD44 signaling of EMT in prostate tumors." (PMID 29108245, 2017). "Although no other study has systematically evaluated IGFBP3 expression as in our study, results from a study of prostate tumor provide some support to our finding." (PMID 17210081, 2007).
pulmonary fibrosis (9 papers, 2012 to 2025). Chronic progressive interstitial lung disorder characterized by the replacement of the lung tissue by connective tissue, leading to progressive dyspnea, respiratory failure, or right heart failure. "We hypothesized that insulin-like growth factor binding protein 3 (IGFBP3) may be the target protein of QRHXF against pulmonary fibrosis." (PMID 36997948, 2023). "Since IGFBP-3 induces SDC2 expression and IGFBP-3 expression and deposition is increased in IPF, we used immunohistochemistry to detect SDC2 protein in vivo in IPF lung tissues and those from patients with SSc-associated pulmonary fibrosis." (PMID 22900087, 2012). "Findings with IGFBP2 are consistent with our previous studies showing increased expression of IGFBP3 and IGFBP5 in IPF and SSc-PF and reinforced the crucial role that IGFBPs and the IGF pathway play in the development and perpetuation of pulmonary fibrosis." (PMID 32210969, 2020). "IGFBP-3 levels are increased in the bronchoalveolar lavage (BAL), lung tissue, and primary fibroblasts of patients with idiopathic pulmonary fibrosis (IPF)." (PMID 22900087, 2012). "IGFBP-3 treatment has been shown to stimulate human primary lung fibroblasts to produce tenascin-C and Collagen 1, supporting a role for IGFBP-3 in promoting ECM deposition in pulmonary fibrosis." (PMID 41226289, 2025). "IGFBP3 plays a role in fibrosis and ECM deposition in idiopathic pulmonary fibrosis." (PMID 35154570, 2022). "Since IGFBP-3 is over-expressed in fibrotic tissues, we examined SDC2 levels in skin and lung tissues of patients with systemic sclerosis (SSc) and lung tissues of patients with idiopathic pulmonary fibrosis (IPF)." (PMID 22900087, 2012).
Sepsis (9 papers, 2013 to 2026). Sepsis is defined as life-threatening organ dysfunction caused by a dysregulated host response to infection. "In the present study, we demonstrated that IGFBP-3 levels below 10.64 were significantly associated with increased 30-day mortality among patients with microbiologically documented sepsis (Log-rank p = 0.007)." (PMID 40724799, 2025). "Not only local IGFBP-3 synthetized in skeletal muscle can be associated with muscle wasting and cachexia in sepsis or in other inflammatory diseases, but also an excess of systemic IGFBP-3 can contribute to muscle atrophy." (PMID 34502376, 2021). "In our study, all cases of Enterococcus bacteremia—a recognized marker of gastrointestinal barrier dysfunction in sepsis —occurred in patients with IGFBP-3 levels below 10.64, reinforcing the potential association between low IGFBP-3 and gut-derived septic complications." (PMID 40724799, 2025). "IGFBP-3 is an independent predictor of 1-year mortality in internal medicine patients with microbiologically confirmed sepsis." (PMID 40724799, 2025). "In sepsis, IGFBP-3 demonstrates IGF-1-independent effects, including the modulation of immune responses, regulation of apoptosis, and influence on inflammation." (PMID 40724799, 2025). "Although this was an observational study, our findings underscore the potential clinical utility of measuring IGFBP-3 levels in sepsis patients admitted to internal medicine units." (PMID 40724799, 2025). "Our findings provide potential explanations for the inverse relationship between serum IGFBP-3 levels and both short- and long-term adverse outcomes in internal medicine patients with sepsis." (PMID 40724799, 2025). "Several preclinical studies have demonstrated the feasibility and benefits of modulating IGF-1/IGFBP-3 expression in acute pathologies, including sepsis." (PMID 40724799, 2025). "To date, only two clinical studies have evaluated IGFBP-3 as a prognostic biomarker in adult patients with sepsis." (PMID 40724799, 2025). "Further information regarding mortality risk in children with sepsis may derive from the evaluation of insulin-like growth factor 1 (IGF-1) and insulin-like growth factor binding protein 3 levels (IGFBP-3)." (PMID 39858517, 2025). "In addition to the CCI, SOFA score, MR-proADM, IGFBP-3, multiple sources of sepsis, and bloodstream infections, age (p = 0.074) and polymicrobial etiology of sepsis (p = 0.097) were also included in the Cox regression analysis." (PMID 40724799, 2025). "Incorporating IGFBP-3 into baseline prognostic evaluations may enhance the prediction of mortality in patients with sepsis." (PMID 40724799, 2025). "IGFBP-3 may also represent a potential therapeutic target in future sepsis research." (PMID 40724799, 2025). "In addition to an increase in GH concentration and a decrease in IGF-I concentration in the course of sepsis, a decrease in the concentration of insulin-like growth factor-binding protein 3 (IGFBP-3) and the increase in IGFBP-1, IGFBP-2, IGFBP-4 are also described." (PMID 34066289, 2021). "Furthermore, reduced free plasma IGF-I by 50% of normal levels, by infusion of IGF binding protein 1, decreased muscle protein synthesis by 25% with decreased phosphorylation of p70s6 kinase, while provision of IGF-I/IGFBP-3 complex improved sepsis induced muscle catabolism." (PMID 23657003, 2013). "IGFBP‐3 is the primary determinant of IGF‐1 levels, reflecting disruption in the GH/IGF‐1 axis during sepsis." (PMID 41555186, 2026). "Animal models of endotoxemia and clinical studies have consistently shown that sepsis reduces circulating levels of both IGF-1 and IGFBP-3, as well as their hepatic gene expression." (PMID 40724799, 2025). "Postoperative sepsis significantly alters the growth hormone/IGF axis, reducing GH-dependent molecule secretion (i.e. IGFBP3) and increasing GH-independent molecule secretion (i.e. IGFBP6)." (PMID 31028944, 2019).
Sepsis (continued). "In this study, serum levels of IGFBP-3, C-reactive protein, procalcitonin, lactate, interleukin-6, and mid-regional pro-adrenomedullin were measured upon admission to the internal medicine unit (IMU) in 139 patients with microbiologically confirmed sepsis." (PMID 40724799, 2025). "Sepsis in humans and experimental sepsis in animals decrease both circulating IGF-1 and IGFBP-3." (PMID 34502376, 2021). "Notably, a single baseline IGFBP-3 measurement demonstrated the same AUROC (0.70) for 1-year mortality as the combined predictive performance of Model 1, which included other independent clinical predictors such as age, SOFA score, and multiple sources of sepsis." (PMID 40724799, 2025).
head and neck squamous cell carcinoma (8 papers, 2013 to 2025). A squamous cell carcinoma that arises from any of the following anatomic sites: lip and oral cavity, nasal cavity, paranasal sinuses, pharynx, larynx, and salivary glands. "In head and neck squamous cell carcinoma, high IGFBP-3 staining was associated with higher clinical stage and decreased time to progression, and was similarly mainly seen in the cytoplasm." (PMID 29623068, 2018). "Several studies have confirmed that IGFBP3 suppresses the invasiveness of endometrial cancer (EC) cells, metastasis in prostate cancer, and angiogenesis in head and neck squamous cell carcinoma (HNSCC)." (PMID 24386080, 2013). "Using NSCLC cells as well as head and neck squamous cell carcinoma, this 2011 study showed that IGFBP-3 leads to decreased ERK1/2 phosphorylation, by direct interaction with the MAPKs (in a non-IGF-dependent manner), thus limiting ELK1’s transcriptional activity." (PMID 40862737, 2025). "IGFBP3 overexpression reduced the cell metastasis of head and neck squamous cell carcinoma (HNSCC), while the silence of IGFBP3 enhanced the metastatic phenotype in vitro and in vivo." (PMID 36660244, 2023). "In addition to the cancer types expected to be affected by the IGFBP-3/TMEM219 system, bladder urothelial carcinoma and head and neck squamous cell carcinoma appear to be significantly associated with TMEM219 but not with IGFBP-3 expression." (PMID 32443727, 2020).
osteoporosis (8 papers, 2008 to 2025). A condition of reduced bone mass, with decreased cortical thickness and a decrease in the number and size of the trabeculae of cancellous bone (but normal chemical composition), resulting in increased fracture incidence. "According to a study, circulating levels of IGF-I and IGFBP-3 were significantly lower in older adults than in the young population, and a low circulating IGF-I and IGFBP-3 level was associated with osteoporosis." (PMID 37035758, 2023). "According to the current stepwise multiple regression analysis, the independent predictors of LS and FN BMD were circulating IGFBP-3 and IL-6, which indicated that circulating cytokines were essential for preventing bone loss and osteoporosis." (PMID 37035758, 2023). "Furthermore, higher levels of IGFBP-3 were also associated with a decreased risk of osteoporosis using the IVW method (OR = 0.999, 95% CI = 0.998-1.000, P = 0.019)." (PMID 38260127, 2023). "Moreover, circulating IGFBP-3 and IL-6 levels were important potential diagnostic biomarkers for postmenopausal women with osteoporosis." (PMID 37035758, 2023). "In addition, the overexpression of IGFBP-3 caused by increased RNA stability might be associated with aging-induced osteoporosis." (PMID 37035758, 2023). "For example, IGFBP-3 is regarded widely as a positive regulator of bone metabolism, thereby offering protection against osteoporosis." (PMID 41305735, 2025). "Age, years since menopause, and circulating IL-6, PTH, and IGFBP-3 were significantly higher in the osteoporosis group compared to the normal group." (PMID 37035758, 2023). "Our findings indicate that genetically proxied higher serum levels of IGF-1, IGFBP-3, IGF-LR1, and CTGF, as well as lower levels of CYR61, are associated with a decreased risk of osteoporosis." (PMID 38260127, 2023). "Our results indicated that the osteoporosis group had significantly high levels of IGFBP-3 than the control group." (PMID 37035758, 2023). "Specifically, our findings indicate that lower levels of IGF-1, IGFBP-3, IGF-LR1, and CTGF, along with higher levels of CYR61, genetically contribute to an increased risk of osteoporosis." (PMID 38260127, 2023). "Compared to the normal women, age, years duration of menopause, and circulating IL-6, PTH, and IGFBP-3 were significantly higher in the osteoporosis women." (PMID 37035758, 2023). "AUC cut-off values (IGFBP-3: 3.65, IL-6: 0.205) were best evaluated for the diagnosis of postmenopausal women with osteoporosis, and the AUC for circulating IGFBP-3 and IL-6 were 0.706 (95% CI 0.594–0.818) and 0.685 (95% CI 0.571–0.798), respectively." (PMID 37035758, 2023). "IGFBP-3 represents another member of the IGF system that exhibited a negative association with the risk of osteoporosis (OR = 0.999, 95% CI = 0.998–1.000, P = 0.019) in UK biobank." (PMID 38260127, 2023). "Therefore, the specific role of IGFBP-3 in bone metabolism and osteoporosis remains controversial." (PMID 37035758, 2023). "In the FinnGen dataset, IGF-1 and IGFBP-3 were not identified to be associated with osteoporosis." (PMID 38260127, 2023). "In addition, IGFBP-3 has been reported to be lower in both males and females with osteoporosis." (PMID 25147565, 2014). "A threshold concentration of circulating IGF-1 is necessary for normal bone growth and IGF-1, IGFBP-3, and ALS play a prominent role in the pathophysiology of osteoporosis." (PMID 25147565, 2014). "This study compared the baseline characteristics of postmenopausal women in the normal and osteoporosis groups and found that the two groups had statistically significant differences in age; years since menopause; circulating IL-6, PTH, and IGFBP-3; LS BMD; and FN BMD." (PMID 37035758, 2023). "So, IGFBP‐3 and IGFBP‐5 decrease in LLIs could be related to both sarcopenia and osteoporosis." (PMID 35932462, 2022).
pancreatic ductal adenocarcinoma (8 papers, 2016 to 2023). An infiltrating adenocarcinoma that arises from the epithelial cells of the pancreas. "The levels of IGFBP3 mRNA and protein were decreased in pancreatic ductal adenocarcinoma, and IGFBP3 was positively associated with OS." (PMID 36660244, 2023). "Further research on these findings suggests that an increased risk of pancreatic ductal adenocarcinoma may be linked to high IGF-1/low IGFBP-3 serum concentrations." (PMID 37623681, 2023). "One study, however, indicated that IGFBP-3 showed biological effects on the chemosensitization of pancreatic ductal adenocarcinoma cells." (PMID 34790580, 2021). "The expression levels of uPA, uPAR, IGF-1, and IGFBP-3 mRNA were significantly greater in pancreatic ductal adenocarcinoma than in benign mucinous cystadenomas’ control tissues." (PMID 33669052, 2021). "Besides, IGFBP3 re-sensitized chemo-resistant pancreatic ductal adenocarcinoma cells by activating apoptosis through Bcl-2 downregulation, Bax upregulation, caspase 3 and caspase 8 activation." (PMID 36660244, 2023). "The IGFBP-3 and uPA mRNAs both increased in pancreatic ductal adenocarcinoma." (PMID 33669052, 2021). "Patients with advanced pancreatic ductal adenocarcinomas and high IGF-1R to low IGFBP-3 ratio expression in the pancreas had worse overall survival rates." (PMID 37623681, 2023).
dementia (7 papers, 2019 to 2025). Loss of intellectual abilities interfering with an individual's social and occupational functions. "In line with our results, higher concentrations of IGFBP-3 were found to be cross-sectionally associated with better cognitive state in women in the Mayo Clinic Study of Ageing and reduced dementia incidence in men." (PMID 33631000, 2021). "Moreover, lower plasma concentration of IGF-1/IGFBP3 increased the risk of prevalent and incident dementia." (PMID 32312329, 2020). "A recent study showed that higher plasma levels of IGF-binding protein 3 (IGFBP-3), a protein essential for IGF-1 physiological action, were associated with decreased risk for dementia." (PMID 31907024, 2020). "Utilizing iTRAQ proteomics, we identified a significant decrease in CSF IGFBP3 levels in PDD patients compared to PD patients without dementia." (PMID 41278191, 2025). "In this study, both total serum IGF-II and IGFBP-3 were associated with age-related cognitive decline and cognitive impairment, but previous associations of total serum IGF-I with cognitive decline and dementia were not replicated." (PMID 30809143, 2019).
endometrial cancer (7 papers, 2003 to 2023). Primary or metastatic malignant neoplasm involving the endometrium (mucous membrane that lines the endometrial cavity). "We found that only the mutation of IGFBP3 will affect its expression in endometrial cancer, and the mutation of IGFBP6 will affect its expression in skin melanoma." (PMID 37088808, 2023). "Serum IGF-I, IGFBP-1, IGFBP-3 and insulin levels seem unrelated to endometrial cancer risk." (PMID 14583772, 2003). "For UCEC, Phosphatidylinositol 3-kinase signaling regulates insulin-like growth factor binding protein-3 expression in endometrial cancer cell lines." (PMID 28881755, 2017). "Another case–cohort study that included 250 incident endometrial cancer patients and 465 controls assessed the association between endometrial cancer risk and serum levels of IGF1, IGFBP3, insulin, and estradiol." (PMID 24904527, 2014). "IGFBP-3 is the predominant IGFBP in the plasma, and IGFBP-3 has been associated with endometrial carcinoma in postmenopausal women." (PMID 22720981, 2012). "We present here results of a population-based case–control study in Sweden, in which we assessed the relationships of endometrial cancer risk with serum levels of fasting insulin, IGF-I, and IGFBP-1, as well as IGFBP-3, IGF's major binding protein in the circulation." (PMID 14583772, 2003). "Among HRT users, higher IGF-I and IGFBP-3 levels were associated with a (nonsignificant) decreased risk of endometrial cancer, while among never users there was no such association." (PMID 14583772, 2003). "We performed a population-based case-control study in Sweden, including 288 endometrial cancer patients and 392 control women and analysed total serum IGF-I, IGFBP-1, IGFBP-3, insulin and BMI levels stratified by disease and hormone replacement therapy status (HRT)." (PMID 14583772, 2003). "In conclusion, our study does not show any evidence of an overall association between endometrial cancer risk and serum levels of IGF-1, IGFBP-1, IGFBP-3, and insulin." (PMID 14583772, 2003). "In addition, genetic variants in IGFBP-3, not IGFBP-1 is associated with the risk of endometrial carcinoma." (PMID 22720981, 2012).
hypothyroidism (7 papers, 2010 to 2025). Abnormally low levels of thyroid hormone. "In the present study, assessment of these high‐affinity binding proteins revealed that hepatic expression of IGFBP1, ‐2, ‐3, and ‐4, and renal expression of IGFBP3 were all significantly impacted by fetal hypothyroidism at least two of the studied time points." (PMID 40693299, 2025). "Subtle changes in hepatic IGF-I and IGFBP-3 mRNA levels together with increased levels of IGFBP-2, a gene that is a marker of delayed development or hypothyroidism in rats, were also shown on PND80." (PMID 22666351, 2012). "Interestingly, however, while IGFBP3 was impacted by fetal hypothyroidism, there was minimal to no impact on expression of the highly related genes IGFBP5 and IGFBP6." (PMID 40693299, 2025).